IL6 (interleukin 6)
Diseases named in the same sentence as IL6 in open-access papers (continued):
Sharing a sentence is not in itself a finding about the gene and the disease.
Crush Syndrome (1 paper, 2022). Severe systemic manifestation of trauma and ischemia involving soft tissues, principally skeletal muscle, due to prolonged severe crushing. "The expression levels of inflammatory cytokines and chemokines (e.g., TNFα, IL-6, CXCL1, CXCL2, CXCR2, CCL2) in crush syndrome were significantly suppressed in TPEN-treated group." (PMID 36114355, 2022).
cryoglobulinemia (1 paper, 2022). Cryoglobulinemia is a type of vasculitis that is caused by abnormal proteins (antibodies) in the blood called 'cryoglobulins.' At cold temperatures, these proteins become solid or gel-like, which can block blood vessels and cause a variety of health problems. "Some studies have explored the roles of the immune system, inflammatory mediators like interleukin-6, and even cryoglobulinemia as contributing factors." (PMID 36059353, 2022).
Cyanosis (1 paper, 2017). Bluish discoloration of the skin and mucosa due to poor circulation or inadequate oxygenation of arterial or capillary blood. "Also, the levels of TNF-α and IL-6 in patients with cyanosis are higher than those in acyanotic individuals." (PMID 28469687, 2017).
Desminopathy (1 paper, 2024). "Moreover, Epi consumption improved blood health parameters, including reduced HOMA‐IR and IL‐6 levels in the desminopathy patient." (PMID 38658362, 2024).
diffuse cutaneous Leishmaniasis (1 paper, 2017). A form of LEISHMANIASIS, CUTANEOUS caused by Leishmania aethiopica in Ethiopia and Kenya, L. pifanoi in Venezuela, L. braziliensis in South America, and L. mexicana in Central America. "Patients with localized cutaneous lesion (LCL) exhibit predominant expression of iNOS, IL-1β, IL-6, MCP-1, TNF-α, and IFN-γ, while anergic diffuse cutaneous leishmaniasis (ADCL) lesions are characterized by the presence of IL-4, IL-5, IL-10, and MIP-1α and the low expression of iNOS." (PMID 28959260, 2017).
disseminated tuberculosis (1 paper, 2025). "He remained highly viremic for KSHV throughout the 2-year study period, during which he was infected with SARS-CoV-2 and developed disseminated tuberculosis, with steadily increasing levels of the inflammatory markers C-reactive protein (CRP), and interleukin-6 (IL-6)." (PMID 39998057, 2025).
duodenitis (1 paper, 2023). Acute or chronic inflammation of the duodenum. "Effects of olmesartan medoxomil raw drug (OM) and zeinmersomes formula (OMZ) on duodenal concentrations of MPO, THF-α, IL-6, MDA, GSH, and cleaved caspase-3 in indomethacin-induced duodenitis in rats (n=8)." (PMID 37255094, 2023). "The duodenitis rats showed significantly higher duodenal levels of myeloperoxidase, TNF-α, IL-6, malondialdehyde, and cleaved caspase-3, a significantly lower GSH level, and histopathological alterations." (PMID 37255094, 2023). "In rats with duodenitis, the concentrations of MPO, TNF-α, IL-6, MDA, and cleaved caspase-3 significantly increased while the GSH level decreased in the duodenal homogenate." (PMID 37255094, 2023).
Dysplastic nevi (1 paper, 2025). "Dysplastic nevi lesions also showed higher int-IL-6 (p=0.04) than serum IL-6 (p=0.8)." (PMID 41268555, 2025).
dystocia (1 paper, 2016). Slow or difficult obstetric labor or childbirth. "In cows, uterine inflammation was characterized by measurement of IL-6, IL-8, IL-1β, interferon (IFN) γ and TNF-α protein by ELISA in vaginal mucus derived from post-parturient cows presenting dystocia or eutocia." (PMID 27152525, 2016). "The vaginal mucus results showed that the concentration of IL-6 was not increased, in contrast to IL-1β, the concentration of which increased in cows that had presented with dystocia three weeks earlier." (PMID 27152525, 2016).
ectodermal dysplasia (1 paper, 2022). "In HC rat lungs at P14, the number of ectodermal dysplasia (ED)-1- and TUNEL-positive cells and level of inflammatory cytokines such as interleukin (IL)-1α, IL-1β, IL-6, and TNF-α were significantly increased." (PMID 35743045, 2022).
egg allergy (1 paper, 2023). A food allergy that is an allergy or hypersensitivity to dietary substances from the yolk or whites of eggs, causing an overreaction of the immune system which may lead to severe physical symptoms. "Following LPS stimulation, IL-6 and IL-1β production was more elevated in both persistent and transient hen’s egg allergy in comparison to healthy controls at follow-up but increased production of TNF-α and IL-8 was unique to infants with persistent hen’s egg allergy." (PMID 36756279, 2023). "Furthermore, children with persistent hen’s egg allergy continued to show higher levels of IL-6, IL-1β and IL-8 in unstimulated CD3-depleted cells compared to children who developed tolerance to hen’s egg at the end of follow-up." (PMID 36756279, 2023).
encephalomalacia (1 paper, 2024). Localized atrophy of the brain parenchyma due to aging, hemorrhage, infarct, or inflammation. "In contrast, IL-6−/− brains exhibited less microglia surrounding the area of encephalomalacia (10X)." (PMID 39334365, 2024).
endometrial disorder (1 paper, 2018). A non-neoplastic or neoplastic disorder that affects the endometrium. "TLR-7/9 and IL-6/8 were shown to be related to endometrial disorders." (PMID 30322386, 2018).
endometrioid ovarian cancer (1 paper, 2023). "In two patients with a diagnosis of endometrioid ovarian cancer, concentrations of Il-6 were 38.87 and 10.1 ng/mL (stage IC and IIIC, respectively)." (PMID 37373969, 2023).
enteropathy-associated T-cell lymphoma (1 paper, 2012). An uncommon mature T-cell lymphoma of intraepithelial lymphocytes. "We set out to investigate the potential use of novel serum parameters, including IL-6, IL-8, IL-17, IL-22, sCD25, sCD27, granzyme-B, sMICA and sCTLA-4 in patients diagnosed with active CD, CD on a GFD, Refractory coeliac disease (RCD) type I and II, and enteropathy associated T-cell lymphoma (EATL)." (PMID 23145841, 2012).
enthesopathy (1 paper, 2019). "IL-6 signal blockade could contribute to the treatment of destructive arthritis, and further studies should be carried out to confirm its potential in the prevention of enthesopathy developed to ossification." (PMID 31200688, 2019).
entrapment neuropathies (1 paper, 2022). "Whereas the literature on IL-6 levels in serum of patients with CTS is conflicting, its contribution to other entrapment neuropathies such as lumbar radicular pain and its severity is well established." (PMID 34224495, 2022).
epilepsy syndrome (1 paper, 2022). A syndrome that has a characteristic cluster of clinical features and/or lectroencephalographic (EEG) findings that reflect underlying epileptic activity. "Particularly, a recent systematic review showed increased levels of IL-1ra, IL-1, IL-6, and CXCL8/IL-8 in several different epilepsy syndromes independently of the underlying etiology." (PMID 35327518, 2022).
epistaxis (1 paper, 2022). Bleeding from the nose. "In parallel with the findings, our previous investigation revealed that IL-6 and TGF-β serum levels were higher in patients with epistaxis who were evaluated in this study." (PMID 35145935, 2022). "Our previous investigation revealed that Interleukin 6 (IL-6) and transforming growth factor (TGF)-β are up-regulated in patients with epistaxis." (PMID 35145935, 2022).
epithelial ovarian tumors (1 paper, 2023). "Recent studies have suggested that tumor necrosis factor-α (TNF-α) promotes the expression of pro-inflammatory cytokines (IL-1β, IL-6 and TNF-α) in human epithelial ovarian tumors." (PMID 37305383, 2023).
esophageal disorder (1 paper, 2021). A non-neoplastic or neoplastic disorder that affects the esophagus. "First, we investigated the IL6 gene and protein expression in the esophagus of individuals without esophageal disorders (healthy), ESCC, and non-tumoral surrounding tissue (NTST)." (PMID 34422669, 2021). "Complementary, we could not detect IL6 immunostaining in the esophagus from individuals without esophageal disorders, while diffuse staining was observed in tumor-surrounding esophageal mucosa." (PMID 34422669, 2021). "Furthermore, IL6 expression was undetectable in 100% of samples from individuals without esophageal disorders, in 60% of tumor-surrounding samples from ESCC patients, but in only one (2.7%) ESCC sample." (PMID 34422669, 2021).
Esophageal stenosis (1 paper, 2018). An abnormal narrowing of the lumen of the esophagus. "Here, we present the case of an immune mucositis and pharyngitis complicated by severe esophageal stenosis developed during nivolumab treatment and refractory to multiple corticosteroid lines but treated successfully with personalized anti-IL-6 blockade therapy (tocilizumab mAbs)." (PMID 30587227, 2018).
Exotropia (1 paper, 2021). A form of strabismus with one or both eyes deviated outward. "IL-6 was significantly higher in patients with concomitant exotropia (4.683 ± 1.329) pg/mL than that in normal group (1.455 ± 0.391) pg/mL, p = 0.0304." (PMID 34659636, 2021). "Firstly, increased exposure and local lesions in concomitant exotropia lead to increased expression of inflammatory factors, especially IL-6 and TNF-α, in the tears." (PMID 34659636, 2021). "The concentration of tear mediators increased obviously in concomitant exotropia, and the IL-6 and TNF-α could be important mediators of inflammation." (PMID 34659636, 2021). "The levels of IL-6, IL-10, IL-17A, IL-12P70, INF-γ, and TNF-α were detected in tears in patients with concomitant exotropia and healthy controls matched by age and gender through the Simoa technology." (PMID 34659636, 2021).
Fa (1 paper, 2020). "PRV-Fa infection can lead to a large increase in the IL6 mRNA expression, whereas inoculation of PRV-ΔgE/ΔgI/ΔTK or PRV-ΔgE/ΔgI/ΔTK-(CD2v) did not cause up-regulation of IL6 expression." (PMID 33198749, 2020).
facioscapulohumeral muscular dystrophy (1 paper, 2023). An autosomal dominant disorder affecting the skeletal muscles of the face, scapula, and upper arm. "Similarly, another study screened for 20 pro-inflammatory cytokines in the serum of patients affected by facioscapulohumeral muscular dystrophy and identified IL-6 as the only cytokine correlating with muscle weakness and disease severity." (PMID 37468473, 2023).
Failure to thrive (1 paper, 2023). Failure to thrive (FTT) refers to a child whose physical growth is substantially below the norm. "We conducted this study to investigate the effect of Lf supplementation in ONS on IL-6 and IL-10 levels in children with failure to thrive and infection." (PMID 38434639, 2023). "Here, we investigate the effect of lactoferrin in ONS towards IL-6 and IL-10 in failure to thrive children with infections during a 90-day intervention." (PMID 38434639, 2023). "Our hypothesis is that lactoferrin influences the immune systems of children with failure to thrive and infections, particularly in relation to IL-6 and IL-10." (PMID 38434639, 2023).
Farber disease (1 paper, 2023). "Additionally, increased plasma levels of IL6, IL10, IL12, CCL2, CCL3, CXCL1, and VEGF and substantial central nervous system defects have been observed in patients with Farber disease." (PMID 37189685, 2023).
gastrointestinal neuroendocrine tumors (1 paper, 2024). "A separate series of gastrointestinal neuroendocrine tumors, including 12 appendiceal tumors, showed frequent expression of IL-6 in these tumors, and a trend toward correlation of IL-6 production with tumor grade." (PMID 38689325, 2024).
giant cell tumor (1 paper, 2012). A benign, intermediate, or malignant tumor that arises from the bone or soft tissue. "The osteoclastogenic cytokines TNF-α, IL-6 and IL-1β have been investigated in giant cell tumors (GCTs) of long bones." (PMID 22157665, 2012). "Key words: Giant cell granuloma, giant cell tumor, multinucleated giant cells, jaw, TNF-alpha, IL-6, IL-1beta,immunohistochemistry." (PMID 22157665, 2012).
growth (1 paper, 2025). The increase in size or mass of an entire organism, a part of an organism or a cell. "Several studies have highlighted the potential of IL6 in distinguishing between malignant and benign ovarian growths, with IL6 concentrations in the circulation typically being higher in OC patients than in those with benign ovarian growths." (PMID 40427188, 2025).
growth retardation (1 paper, 2015). "Some studies have shown that Interleukin-6 (IL6) was significantly elevated in the cord blood from neonates born small with intrauterine growth retardation." (PMID 25806090, 2015).
Heart block (1 paper, 2024). Impaired conduction of cardiac impulse occurring anywhere along the conduction pathway. "Our data suggests a potential role for IL-18 in IL-6 trans-signaling-linked pathological ion channel remodeling, action potential phenotypes, and increased propensity for heart block." (PMID 39063055, 2024).
Hemiparesis (1 paper, 2015). Loss of strength in the arm, leg, and sometimes face on one side of the body. "hyperEPO alone (MCP-1, yellow) was associated with significantly greater risk of hemiparesis, whereas ISSI alone (IL-6 and VEGF-R1, orange) was associated with significantly higher risk compared to referent newborns." (PMID 25793991, 2015).
hemorrhoid (1 paper, 2024). Dilated veins in the anal canal. "Inflammatory cytokines and enzymes, such as interleukin-6 (IL-6), interleukin-17 (IL-17), tumor necrosis factor-alpha (TNF-α), nitric oxide (NO), inducible nitric oxide synthase (iNOS), and matrix metalloproteinases (MMPs), show a high correlation with the pathogenesis of hemorrhoids." (PMID 38893547, 2024).
hepatic lymphoma (1 paper, 2012). "It is critical to exclude the possibility that the observed severe HMNC infiltration in dnTGFβRII IL-6−/− littermates actually reflects severe autoimmune liver inflammation rather than hepatic lymphoma." (PMID 23145171, 2012).
hereditary angioedema (1 paper, 2024). Hereditary angioedema (HAE) is a genetic disease characterized by the occurrence of transitory and recurrent subcutaneous and/or submucosal edemas resulting in swelling and/or abdominal pain. "Besides, this study hinted the repurposing values of some proteins approved for other diseases, such as prekallikrein for hereditary angioedema and IL-6 sRa for inflammatory diseases, in VTE treatment." (PMID 38029854, 2024).
hereditary thrombophilia (1 paper, 2024). "According to these outcomes, patients with hereditary thrombophilia may experience recurrent pregnancy losses with elevated levels of IL-6 and TNF-α." (PMID 38533322, 2024).
heroin addiction (1 paper, 2023). "The results of this study show that different polyphenols target specific behavioral domains of heroin addiction in a CPP model and modulate the increase in striatal inflammatory cytokines TNF-α and IL-6 observed during naloxone-precipitated heroin withdrawal." (PMID 37112606, 2023).
histiocytic sarcoma (1 paper, 2016). An aggressive malignant neoplasm with a poor response to therapy, usually presenting as stage III/IV disease. "Prior studies have also evaluated other pro-inflammatory cytokines in the context of histiocytic sarcoma, including IL-6." (PMID 27105514, 2016). "Additional mechanistic insight will be necessary to better define the relationship between NLRX1, IL-6 and histiocytic sarcoma pathogenesis." (PMID 27105514, 2016). "While we focused on IL-6 and CCL2, many of the other genes identified are also highly interesting and should provide significant insight related to histiocytic sarcoma pathogenesis." (PMID 27105514, 2016).
histoplasmosis (1 paper, 2025). A disease caused by the fungus Histoplasma capsulatum. "In our study, TNF-α and IL-1β together with IL-6 and IL-18 showed the highest values, with statistical differences for the group of HIV patients and Hc suggesting that these cytokines play a role in the local inflammatory processes of histoplasmosis in HIV patients." (PMID 40558960, 2025).
HIVinfection (1 paper, 2008). "Increased cytokine levels in semen have been established in HIVinfection (IL-1β), and genital infectionssuch as Chlamydia trachomatis (IL-8) and Neisseriagonorrhoeae (IL-6, IL-8)." (PMID 18615190, 2008).
homeostasis (1 paper, 2021). "A previous study demonstrated that IL-1β, IL-6, and TGF-β promotes the differentiation of naive T cells into Th17 cells and in turn suppresses Treg differentiation, leading to homeostasis disorders." (PMID 33575330, 2021).
homocystinuria (1 paper, 2021). An autosomal recessive inherited metabolic disorder caused by mutations in the CBS, MTHFR, MTR, and MTRR genes. "Proinflammatory cytokines other than IL-6, namely IL-1α, IL-1β and TNF-α, are increased in a mouse model of homocystinuria and a range proinflammatory cytokines and chemokines [IL-1α, IL-6, TNF-α, IL-17, IL-12 (p70), MIP-1α and MIP-1β] are also elevated in homocystinuria patients." (PMID 34251022, 2021).
hydatid disease (1 paper, 2022). "Considering P < 0.05 to indicate statistical significance, the following clinical indexes were found to be significant: age, monocyte count, IL-6 level, history of hydatid disease, HS-CRP level, density, size, D-dimer level, eosinophil count and temperature." (PMID 36181541, 2022).
hyper-IgM syndrome (1 paper, 2016). A primary immune deficiency disorder characterized by defective CD40 signaling; via B cells affecting class switch recombination (CSR) and somatic hypermutation. "ELISA was used to determine whether BCL2+IL6+AID− mice exhibited changes in serum Ig patterns that mimic the hyper-IgM syndrome of patients with WM." (PMID 27813533, 2016).
Hyperactivity (1 paper, 2021). Hyperactivity is a condition characterized by constant and unusually high levels of activity, even in situations where it is deemed inappropriate. "However, this test could predict a subset of patients with a specific immune response (i.e., early IgG response and IL-6-dependent immune hyperactivity), and could suggest targeted treatment options (e.g., targeting IL-6 and its pathways)." (PMID 33910993, 2021).
Hyperoxaluria (1 paper, 2023). Increased excretion of oxalates in the urine. "Previous studies have also found that renal expression of IL6 was elevated in hyperoxaluria mice." (PMID 37051106, 2023).
Hypertonia (1 paper, 2020). A condition in which there is increased muscle tone so that arms or legs, for example, are stiff and difficult to move. "Regarding tone disorders, we found significantly higher levels of proinflammatory mediators (GM-CSF, IL-6, and IL-17A), and the anti-inflammatory IL10, in children with hypertonia than in those with hypotonia." (PMID 33584663, 2020).
hypopituitarism (1 paper, 2023). A condition of diminution or cessation of secretion of one or more hormones from the anterior pituitary gland. "In a cross-sectional study that enrolled 53 women with hypopituitarism and 111 healthy control women, interleukin-6 (IL-6) and CRP concentration were significantly higher in women with hypopituitarism than in healthy controls and were attributed to GH and estrogen deficiency." (PMID 36742387, 2023).
idiopathic interstitial pneumonia (1 paper, 2010). A class of diffuse lung diseases that typically affect the pulmonary interstitium, although some also have a component affecting the airways (for instance, Cryptogenic organizing pneumonitis). "Lymphocytosis in the lung lesions of patients with idiopathic interstitial pneumonia is associated with an increased amount of IL-6 in the lung." (PMID 20137099, 2010).